RPL13A (ribosomal protein L13a)
Description:
Associated with ribosomes but is not required for canonical ribosome function and has extra-ribosomal functions. Component of the GAIT (gamma interferon-activated inhibitor of translation) complex which mediates interferon-gamma-induced transcript-selective translation inhibition in inflammation processes. Upon interferon-gamma activation and subsequent phosphorylation dissociates from the ribosome and assembles into the GAIT complex which binds to stem loop-containing GAIT elements in the 3'-UTR of diverse inflammatory mRNAs (such as ceruplasmin) and suppresses their translation. In the GAIT complex interacts with m7G cap-bound eIF4G at or near the eIF3-binding site and blocks the recruitment of the 43S ribosomal complex. Involved in methylation of rRNA.
Synonyms: L13A; uL13; TSTA1
Tractability: Small molecule: an approved drug acts on it; a structure with a bound ligand is known; a high-quality ligand is known. PROTAC: ubiquitination databases record sites on it; its protein half-life has been measured; a small molecule that binds it is known. Other modalities: a drug acting on it is in phase 2 or 3 trials.
Target class: Other cytosolic protein
Gene: Protein-coding gene on chromosome 19 (49,487,510 to 49,493,057, forward strand). Ensembl gene ENSG00000142541.
Subcellular location: Cytoplasm
Subcellular location (Human Protein Atlas): Cytosol; Nucleoli
Pathways (Reactome):
Metabolism of proteins: Eukaryotic Translation Termination; Formation of a pool of free 40S subunits; GTP hydrolysis and joining of the 60S ribosomal subunit; L13a-mediated translational silencing of Ceruloplasmin expression; PELO:HBS1L and ABCE1 dissociate a ribosome on a non-stop mRNA; Peptide chain elongation; Ribosome Quality Control (RQC) complex extracts and degrades nascent peptide; SRP-dependent cotranslational protein targeting to membrane; ZNF598 and the Ribosome-associated Quality Trigger (RQT) complex dissociate a ribosome stalled on a no-go mRNA
Metabolism of RNA: Major pathway of rRNA processing in the nucleolus and cytosol; Nonsense Mediated Decay (NMD) enhanced by the Exon Junction Complex (EJC); Nonsense Mediated Decay (NMD) independent of the Exon Junction Complex (EJC)
Cellular responses to stimuli: Response of EIF2AK4 (GCN2) to amino acid deficiency
Developmental Biology: Regulation of expression of SLITs and ROBOs
Disease: Viral mRNA Translation
Metabolism: Selenocysteine synthesis
Gene Ontology:
Molecular function: RNA binding; structural constituent of ribosome; mRNA binding
Biological process: cellular response to type II interferon; negative regulation of formation of translation preinitiation complex; negative regulation of translation; cytoplasmic translation; negative regulation of myoblast fusion; spermatogenesis; striated muscle contraction; translation
Cellular component: cytoplasm; cytosolic large ribosomal subunit; cytosolic ribosome; focal adhesion; GAIT complex; membrane; nucleolus; nucleus; ribonucleoprotein complex; cytosol; large ribosomal subunit; ribosome; synapse
Genetic constraint (gnomAD): Loss-of-function variants: 4 observed, 30.22 expected, observed/expected ratio (o/e) 0.13, 90% interval 0.064 to 0.3. The upper end of that interval is the gene's LOEUF score, 0.3, which puts it in group 1 of 6, group 1 being the genes least tolerant of losing a copy. Missense variants: 190 observed, 258.67 expected, observed/expected ratio (o/e) 0.73, 90% interval 0.65 to 0.83. Synonymous variants: 106 observed, 95.47 expected, observed/expected ratio (o/e) 1.11, 90% interval 0.95 to 1.3.
Homologues: Orthologues: chimpanzee RPL13A (100% identical), dog RPL13A (99% identical), mouse Rpl13a (96% identical), tropical clawed frog rpl13a (91% identical), zebrafish rpl13a (87% identical), rabbit RPL13A (61% identical), Drosophila melanogaster RpL13A (57% identical), Caenorhabditis elegans rpl-16 (53% identical). Paralogues in human: MRPL13 (24% identical).
Diseases named in the same sentence as RPL13A in open-access papers:
RPL13A is named in the same sentence as 54 diseases in open-access papers, as found by Europe PMC text mining. Sharing a sentence is not in itself a finding about the gene and the disease. The quoted sentences say what the papers report.
ovarian carcinoma (8 papers, 2014 to 2025). A malignant neoplasm originating from the surface ovarian epithelium. "RPL13A, the most suitable reference gene for analysing the transcription profile of ovarian cancer cells following treatment with PTX and HCPT." (PMID 35057823, 2022). "Accordingly, in this study, TBP should be superior to RPL13A and, therefore, added into the stable combination for normalization in epithelial ovarian cancer studies." (PMID 24776823, 2014). "Recently, it is reported that B2M and 18S RNA are suitable internal reference genes in serum stimulated samples; GUSB and PPIA are believed to serve as internal reference genes in ovarian cancer, while RPL13A is identified to stably transcript in ovarian cancer cells treated with PTX and HCPT." (PMID 28184026, 2017). "Interestingly, the GMR of the anaplastic cell line (RPL13A) was found as the most stably expressed gene in two ovarian cancer cell lines (UACC–1598 and SKOV3) subjected to two widely used anticancer treatment, confirming the major role played by this gene in stabilizing the cancer phenotype." (PMID 31349573, 2019). "Previous studies have reported that under normoxic conditions, the most stably expressed genes in ovarian cancer cells are GAPDH/TBP, while under hypoxic conditions, the most stable candidate housekeeping genes are RPL13A/SDHA." (PMID 38166541, 2024). "Interestingly, RPL13A has been reported to be stable independent of disease progression in ovarian cancer patients (n = 50; 25 normal, benign or borderline patient samples, 25 malignant epithelial tumors), and a suitable reference gene for qPCR." (PMID 32133296, 2020).
breast carcinoma (5 papers, 2016 to 2025). "The Ct values varied from 16.35 (RPL13A) to 24.57 (QRICH1) across various breast cancer tissues." (PMID 34895237, 2021). "In addition, GUSB, TUBA1A, RPL13A, and B2M, which previous studies suggested being stable RGs in breast cancer research, and two classical RGs, ACTB and GAPDH, were also considered." (PMID 34895237, 2021). "The total score of all algorithms combined was lowest for ACTB, followed by RPL13a and GAPDH, making these genes the most stable ones in the combined data set in the breast cancer cell lines studied." (PMID 40133575, 2025). "In the breast cancer tissue group DNAJC8, RPL13A, and TARDBP were the most stably expressed genes, while ACTB, B2M, and GAPDH were the least stably expressed genes." (PMID 34895237, 2021). "In the breast cancer cell group, THRAP3, DNAJC8, and RPL13A were the three most stably expressed genes, while TUBA1A, B2M, and ACTB were the least stably expressed genes." (PMID 34895237, 2021). "In previous breast cancer studies, commonly used RGs included beta-actin (ACTB), glyceraldehyde-3-phosphate dehydrogenase (GAPDH), beta-glucuronidase (GUSB), ribosomal protein L13a (RPL13A), and tubulin alpha 1a (TUBA1A)." (PMID 34895237, 2021). "Analysing breast cancer gene expression data sets provided little evidence for expression of the non-coding RNAs AC005256.1 and AC011747.4, or the RPL13A pseudogene ENSG00000226945, so these were omitted from further consideration." (PMID 36198774, 2022).
melanoma (4 papers, 2018 to 2023). A malignant, usually aggressive tumor composed of atypical, neoplastic melanocytes. "The most frequent non-coding mutation in the melanoma cohort occurs in an ETS binding site in the RPL13A promoter, which is also recurrent in other melanoma mutation data sets." (PMID 37169747, 2023). "Multiple sites, as exemplified by the Ets site in the RPL13A promoter, are highly recurrent in melanoma, but appear to be unlikely cancer drivers based on function of the gene regulated by the mutated promoter." (PMID 30485262, 2018). "Four additional melanoma somatic mutation hotspots (> 3 mutations) were present in the assayed regions: TERT, encoding one subunit of telomerase and known to be frequently activated by somatic promoter mutations in cancer, and three ETS-related sites (RPL13A, AP3D1 and EGR1)." (PMID 37169761, 2023).
viral infection (4 papers, 2015 to 2025). "This study highlights the expanded role of extra-ribosomal uL13/RPL13a as a critical component of the innate immune response to viral infections." (PMID 39766272, 2024).
prostate carcinoma (3 papers, 2007 to 2018). A carcinoma that arises from epithelial cells of the prostate gland. "A particularly striking example in this regard, is the contrast between our results and the reported in prostate cancer tissue, where HPRT1 was the most stable gene, and RPL13A and ACTB were the most unstable." (PMID 18226276, 2008). "Furthermore, in prostate cancer, ACTB, RPL13A and HMBS showed significant differences between cancer and noncancerous tissues." (PMID 17640361, 2007).
COVID-19 (2 papers, 2022 to 2025). A disease caused by infection with severe acute respiratory syndrome coronavirus 2. "In COVID-19, these included RPL13A, RPL6, RPL13, RPLP2, RPS11, UBA52, and the ribosomal pseudogene RPL13AP20." (PMID 41020849, 2025).
diabetes (2 papers, 2019 to 2025). "Loss of Rpl13a snoRNAs protects animals in models of sepsis and diabetes, but the mechanism for this phenotype has remained elusive, since it does not depend on rRNA modification." (PMID 31363086, 2019).
embryonal tumors (2 papers, 2023 to 2024). "In embryonal tumors, the topmost DE genes included many ribosome-associated genes like RPS2, RPLP1, and RPL13A as well as histone H3.3 related genes like H3F3A and H3F3B." (PMID 36865335, 2023).
epilepsy (2 papers, 2024). A brain disorder characterized by episodes of abnormally increased neuronal discharge resulting in transient episodes of sensory or motor neurological dysfunction, or psychic dysfunction. "A lithium–pilocarpine model of epilepsy also demonstrated that Ppia, but not Rpl13a, exhibited consistent expression in the dorsal and ventral regions of the hippocampus." (PMID 39456907, 2024).
fungal infection (2 papers, 2016 to 2020). "After fungal infection, RPS3, RPS18, and RPL13a expressed stably in T. castaneum." (PMID 33085726, 2020). "The best reference genes for use as normalizers in our study were EF, EIF4A and GAPDH for the different developmental stages and body parts; EF, RPL13A and EIF4A for the low-temperature challenge; and EF, EIF4A and TUB for both the fungal infection and dietary treatments." (PMID 27392023, 2016). "The 3 most stable genes were EIF4A, GAPDH and TUB for the different developmental stages; EIF4A, GAPDH and EF for the different body parts; EF, RPL13A and GAPDH for the low-temperature challenge; G6PDH, 18S and EIF4A for fungal infection; and EF, GAPDH and TUB for the different diets treatment." (PMID 27392023, 2016).
glioma (2 papers, 2021 to 2022). A benign or malignant brain and spinal cord tumor that arises from glial cells (astrocytes, oligodendrocytes, ependymal cells). "The PPIA, H2AFZ, and HPRT1 genes have been proven to be the most stable reference genes in mouse oocytes and preimplantation-stage embryos under different culture conditions, while HPRT1 and RPL13A have been demonstrated to be the most stable reference genes in glioma stem cells (GSCs)." (PMID 37170359, 2022).
myocardial infarction (2 papers, 2011 to 2021). Gross necrosis of the myocardium, as a result of interruption of the blood supply to the area, as in coronary thrombosis. "Hprt, Rpl13a and Tpt1 are a set of stably expressed reference genes for accurate gene expression normalization in myocardial infarction studies in mice." (PMID 21858224, 2011). "Using the geNorm algorithm, we were able to identify a set of three reference genes, Hprt, Rpl13a and Tpt1, which can be used for accurate gene expression normalization in qPCR experiments on mouse myocardial infarction tissue." (PMID 21858224, 2011).
Obesity (2 papers, 2016 to 2026). Accumulation of substantial excess body fat. "By contrast, our study confirms that RPL13A and EEF1A1 are stable reference genes for VAT or SAT samples from subjects with different degrees of obesity and IR." (PMID 27304673, 2016).
osteosarcoma (2 papers, 2022 to 2023). A usually aggressive malignant bone-forming mesenchymal neoplasm, predominantly affecting adolescents and young adults. "In response to stress, uS3/RPS3, uS4/RPS9, uS17/RPS11, eS24/RPS24, eL6/RPL6, uL13/RPL13A, eL14/RPL14, eL30/RPL30, eL42L/RPL36AL, and RACK1 in U2OS (human osteosarcoma) cells have O-linked β-N-acetylglucosamine (O-GlcNAc) modifications." (PMID 37047306, 2023).
schizophrenia (2 papers, 2015 to 2017). A major psychotic disorder characterized by abnormalities in the perception or expression of reality. "These include: VAT‐1, DAD‐1, PAQR9, BCKD, BDH, Prickle4, PP2A, RPL13A, SPRED2, KLP, FAM36A, NAB1, CLSTN3, PEDF‐R, and FZD3 (Frizzled gene previously associated with different psychopathologies, most notably Schizophrenia)." (PMID 27696737, 2017). "This analysis demonstrated that the levels of eIF2α, RPL13, RPL13A, RPL18A, RPL27A and RPL32 were reduced in schizophrenia patient-derived cells in comparison with controls." (PMID 26485547, 2015).
skin cancer (2 papers, 2023). "We also found genes that, to our knowledge, have no previously reported driver NCVs with TFA-BT NCVs in at least 5% of tumors within certain cancer types, such as RPL13A (bladder and skin cancer), TEDC2 (skin cancer), and PES1 (skin cancer)." (PMID 36808133, 2023).
acute pancreatitis (1 paper, 2016). An acute inflammatory process that leads to necrosis of the pancreatic parenchyma. "Thus, we recommend the use of RPL-13A or a combination of RPL-13A and YWHAZ for normalization in qRT-PCR analyses of gene expression in mouse models of acute pancreatitis." (PMID 27069927, 2016).
anaplastic thyroid cancer (1 paper, 2019). "Interestingly, RPL13A was also found to be the most influential gene in 8505C (anaplastic thyroid cancer) cells and to have a high GCH (63.26) in the BCPAP cells." (PMID 31349573, 2019).
Arthritis (1 paper, 2023). Inflammation of a joint. "In a past study, HPRT1, B2M, and RPL13A were the stable genes in the arthritic joints of the KbxN serum transfer arthritis model, and the mRNA expression level of GAPDH significantly decreased with an increase in joint inflammation." (PMID 37894839, 2023).
bladder cancer (1 paper, 2020). "Under our experimental conditions, HIF-1α-target gene CA9 but not HIF-1α-unrelated RPL13A was induced in T24 cells following CDDP exposure, indicating that CDDP enhances the expression and the transcriptional activity of HIF-1α in bladder cancer cells." (PMID 32522234, 2020).
Cerebral ischemia (1 paper, 2010). Restriction of arterial blood supply to the brain associated with insufficient oxygenation to support the metabolic requirements of the tissue. "In this study we demonstrate that EF1α, RPL13a and YWHAZ are suitable genes for the RT-qPCR analysis and comparison of several sources of human MSC during in vitro characterization and differentiation as well as in an ex vivo animal model of global cerebral ischemia." (PMID 20716364, 2010).
chronic pancreatitis (1 paper, 2016). A chronic inflammatory process causing damage and fibrosis of the pancreatic parenchyma. "Jesnowski and colleagues found that ribosomal protein L13A (RPL-13A) is a reliable standard for chronic pancreatitis." (PMID 27069927, 2016).
colitis (1 paper, 2018). Inflammation of the colon. "Myeloid specific knockout of Rpl13a renders the host susceptible to LPS-induced endotoxaemia and DSS colitis." (PMID 30542349, 2018).
Duchenne muscular dystrophy (1 paper, 2021). Duchenne muscular dystrophy (DMD) is a neuromuscular disease characterized by rapidly progressive muscle weakness and wasting due to degeneration of skeletal, smooth and cardiac muscle. "In this study we have identified reference genes suitable for use in brain tissue from two important animal models of Duchenne muscular dystrophy, the DE50-MD dog and themdx mouse.SDHA, UBC andYWHAZ had stable expression in canine brain, andGAPDH, RPL13A andCYC1 in murine brain." (PMID 37942409, 2021).
Fanconi anemia (1 paper, 2015). Fanconi anemia (FA) is a hereditary DNA repair disorder characterized by progressive pancytopenia with bone marrow failure, variable congenital malformations and predisposition to develop hematological or solid tumors. "We performed DRIP-qPCR in four human genes, APOE, RPL13A, EGR1 and BTBD19 in well-established cell lines derived from Fanconi Anemia patients." (PMID 26584049, 2015).
fibrosarcoma (1 paper, 2020). A malignant mesenchymal fibroblastic neoplasm affecting the soft tissue and bone. "Real-time PCR analysis showed that silencing SAPCD2 decreased expression levels of multiple downstream genes of the Hippo pathway, including CTGF, CYR61, SOX9, HOXA1, RPL13A, and PPIA in fibrosarcoma cells." (PMID 33384953, 2020).
glioblastoma (1 paper, 2019). The most malignant astrocytic tumor (WHO grade IV). "Moreover, to investigate the reliability and the integrity of our NGS transcription data results for each compartment, we evaluated the expression of genes considered as housekeeping candidates in human normal brain tissue, glioblastoma and endothelial cells (RPL13A, RPL4, CYC1, EIF4A2)." (PMID 31231613, 2019).
Infertility (1 paper, 2023). "The topological analysis of the WGCN of the testis transcriptional cell atlas highlighted important somatic genes in this network, including RPL39, RPL10, RPL13A, FTH1, RPS2, and RPL18A, which have been reported to be associated with infertility." (PMID 38012716, 2023).
ischemia (1 paper, 2010). A hypoperfusion of the BLOOD through an organ or tissue caused by a PATHOLOGIC CONSTRICTION or obstruction of its BLOOD VESSELS, or an absence of BLOOD CIRCULATION. "In addition, species-specific primer pairs for human RPL13a and YWHAZ as well as rat RPL13a were found to be suitable for RT-qPCR analysis in the cross-species scenario of human MIAMI cells injected into a rat hippocampal organotypic model of ischemia." (PMID 20716364, 2010).
male infertility (1 paper, 2023). The inability of the male to effect fertilization of an ovum after a specified period of unprotected intercourse. "We also identified key somatic cell genes, including RPL39, RPL10, RPL13A, FTH1, RPS2, and RPL18A, which were highly influential in the weighted gene co-expression network of the testis transcriptional cell atlas and have been previously implicated in male infertility." (PMID 38012716, 2023).
metastatic cancer (1 paper, 2021). A carcinoma which has spread from the original site of growth to another anatomic site. "Although Rpl29 and Rpl13a were downregulated in cancer cells of mouse models compared to normal mammary epithelial cells, these two genes were significantly upregulated in metastatic cancer cells compared to primary cancer cells." (PMID 34497807, 2021).
mucinous ovarian tumors (1 paper, 2014). "With M values less than 1.5, HRPT1, RPL13A, ACTB, TBP, PBGD, and RPLP0 were recommended as a dependable normalizing combination for ovarian mucinous tumors." (PMID 24776823, 2014).
Ogden syndrome (1 paper, 2025). Ogden syndrome is a rare, genetic progeroid syndrome characterized by a variable phenotype including postnatal growth delay, severe global developmental delay, hypotonia, non-specific dysmorphic facies with aged appearance and cryptorchidism, as well as cardiac arrthymias and skeletal anomalies. "Combined analyses of Ogden syndrome cellular models and HeLa cancer models identified a subset of common N-terminally acetylated proteins, including GCN1, ELOA, PPIA, RPL13A, RPP30, and SAE1." (PMID 40558489, 2025).